ATOH8 (atonal bHLH transcription factor 8)
Description:
Transcription factor that binds a palindromic (canonical) core consensus DNA sequence 5'-CANNTG-3' known as an E-box element, possibly as a heterodimer with other bHLH proteins. Regulates endothelial cell proliferation, migration and tube-like structures formation. Modulates endothelial cell differentiation through NOS3. May be implicated in specification and differentiation of neuronal cell lineages in the brain (By similarity). May participate in kidney development and may be involved in podocyte differentiation (By similarity). During early embryonic development is involved in tissue-specific differentiation processes that are dependent on class II bHLH factors and namely modulates the differentiation program initiated by the pro-endocrine factor NEUROG3 (By similarity). During myogenesis, may play a role during the transition of myoblasts from the proliferative phase to the differentiation phase (By similarity). Positively regulates HAMP transcription in two ways, firstly by acting directly on the HAMP promoter via E-boxes binding and indirectly through increased phosphorylation of SMAD protein complex. Repress NEUROG3-dependent gene activation in a gene-specific manner through at least two mechanisms; requires only either the sequestering of a general partner such as TCF3 through heterodimerization, either also requires binding of the bHLH domain to DNA via a basic motif (By similarity).
Synonyms: bHLHa21; hATH6; FLJ14708
Tractability: No criterion of Open Targets' tractability assessment is met for any kind of drug.
Gene: Protein-coding gene on chromosome 2 (85,751,344 to 85,791,383, forward strand). Ensembl gene ENSG00000168874.
Subcellular location: Nucleus; Nucleus speckle; Cytoplasm
Subcellular location (Human Protein Atlas): Nucleoplasm
Gene Ontology:
Molecular function: DNA-binding transcription factor activity; E-box binding; DNA-binding transcription factor activity, RNA polymerase II-specific; DNA-binding transcription factor binding; protein dimerization activity
Biological process: negative regulation of endothelial cell proliferation; negative regulation of gene expression; positive regulation of DNA-templated transcription; positive regulation of endothelial cell differentiation; positive regulation of endothelial cell migration; positive regulation of miRNA transcription; positive regulation of SMAD protein signal transduction; tube formation; anatomical structure morphogenesis; formation of primary germ layer; myoblast proliferation; negative regulation of DNA-templated transcription; positive regulation of transcription by RNA polymerase II
Cellular component: nuclear speck; nucleoplasm; nucleus; chromatin; cytoplasm
Genetic constraint (gnomAD): Loss-of-function variants: 9 observed, 19.77 expected, observed/expected ratio (o/e) 0.46, 90% interval 0.27 to 0.79. The upper end of that interval is the gene's LOEUF score, 0.79, which puts it in group 3 of 6, group 1 being the genes least tolerant of losing a copy. Missense variants: 448 observed, 374.67 expected, observed/expected ratio (o/e) 1.2, 90% interval 1.11 to 1.29. Synonymous variants: 224 observed, 183.98 expected, observed/expected ratio (o/e) 1.22, 90% interval 1.09 to 1.36.
Homologues: Orthologues: chimpanzee ATOH8 (99% identical), macaque ATOH8 (97% identical), pig ATOH8 (92% identical), rabbit ATOH8 (91% identical), rat Atoh8 (88% identical), mouse Atoh8 (88% identical), guinea pig ATOH8 (86% identical), dog ATOH8 (76% identical), tropical clawed frog atoh8 (44% identical), zebrafish atoh8 (37% identical), Drosophila melanogaster net (27% identical). Paralogues in human: NEUROD2 (17% identical), NEUROD1 (16% identical), NEUROD6 (15% identical), NEUROD4 (14% identical), NEUROG1 (14% identical), NEUROG3 (14% identical), BHLHE22 (13% identical), NEUROG2 (13% identical), OLIG2 (12% identical), OLIG3 (12% identical), ATOH1 (12% identical), BHLHA15 (12% identical), and 3 more.
Diseases named in the same sentence as ATOH8 in open-access papers:
ATOH8 is named in the same sentence as 40 diseases in open-access papers, as found by Europe PMC text mining. Sharing a sentence is not in itself a finding about the gene and the disease. The quoted sentences say what the papers report.
breast carcinoma (6 papers, 2016 to 2025). "A recent study performed to investigate the role of Atoh8 in breast cancer has not only identified this novel splice variant but also attributed it to have a discrete function compared to that of the originally identified Atoh8." (PMID 35053134, 2022). "Functional assays on DNASE2 and ATOH8 revealed their opposing roles in breast cancer cell behavior, consistent with MR analysis predictions." (PMID 40282270, 2025). "In summary, our findings revealed that DNASE2 significantly promoted the migration and invasion of breast cancer cells, whereas ATOH8 dramatically inhibited proliferation, migration, and invasion." (PMID 40282270, 2025). "Given the challenges associated with experimental studies on TTC23, we deemed it necessary to further elucidate the biological functions of DNASE2 and ATOH8 in the context of breast cancer." (PMID 40282270, 2025). "Functional experiments revealed that ATOH8 suppresses breast cancer cell proliferation, migration, and invasion, while DNASE2 promotes these processes." (PMID 40282270, 2025). "Functional studies were conducted to assess the phenotypic effects of siRNA-mediated knockdown of DNASE2 and ATOH8 with siRNA in the breast cancer cell lines MCF-7 and MDA-MB-231." (PMID 40282270, 2025). "Scratch assays demonstrated silencing ATOH8 obviously facilitated wound healing, while knockdown DNASE2 had the opposite effect, implicating the promotive and inhibitory roles of DNASE2 and ATOH8 in the migration of breast cancer cells, respectively." (PMID 40282270, 2025). "Through Mendelian randomization analysis, 12 key genes were found to be causally linked to breast cancer pathogenesis, including DNASE2 and ATOH8, which were further validated in external datasets." (PMID 40282270, 2025). "The functional assays proved the contribution of DNASE2 and ATOH8 in the progression of breast cancer by modulating the proliferation, migration, and invasion of cancer cells." (PMID 40282270, 2025). "Strikingly, functional assays of the less-reported genes DNASE2 and ATOH8 demonstrated their involvement in breast cancer pathogenesis through modulating proliferation, migration, and invasion of cancer cells." (PMID 40282270, 2025). "In breast cancer, a study was performed to identify the enriched tissue-specific transcription factors which connected Atoh8 to the dysregulated transcriptional regulatory network which affected the proliferation, differentiation, cell adhesion and metastasis." (PMID 35053134, 2022). "In cancer studies, ATOH8 was an emerging star with ambiguity functions: it was proposed both as oncogene or tumor suppressor gene in glioblastoma, breast cancer and HCC." (PMID 27049918, 2016). "Recently, ATOH8 was identified as a downstream effector of IL6-STAT3 signaling that compromised long-term surviving in breast cancer." (PMID 27049918, 2016). "Notably, recent studies have identified a novel isoform of ATOH8, ATOH8-V1, which was highly expressed in breast cancer and promoted metastasis by regulating RhoC." (PMID 40282270, 2025). "By exploring Oncomine data base, we found that ATOH8 decreased expression in bladder cancer, breast cancer, lung cancer, ovarian cancer and prostate cancer, whereas it increased expression in brain and CNS cancer and esophageal cancer, suggesting the divergent function of ATOH8 in human cancers." (PMID 27049918, 2016). "Furthermore, we identified several unreported tissue-specific TFs that may contribute to breast cancer, including ATOH8, DMRT2, TBX15 and ZNF367." (PMID 28036274, 2017). "In contrast, the expression levels of PIK3R1, PNPLA2, ATOH8, TTC23, and CWF19L2 were dramatically lower in breast cancer samples than in healthy controls (p < 0.05)." (PMID 40282270, 2025). "Except for ATOH8, DNASE2, and TTC23, the involvement of the other nine co-expressed genes has been reported in breast cancer." (PMID 40282270, 2025).
breast carcinoma (continued). "Drug sensitivity analysis indicated significant correlations between several commonly used clinical drugs for breast cancer treatment and DNASE2/ATOH8 expression." (PMID 40282270, 2025). "In addition, the contrasting effects of ATOH8 and DNASE2 on cell proliferation and migration further underscore their potential as therapeutic targets in breast cancer." (PMID 40282270, 2025). "Considering the lack of research on the genes DNASE2 and ATOH8 in the context of breast cancer, we deemed it necessary to further elucidate their functions in breast cancer progression." (PMID 40282270, 2025). "Notably, several commonly used clinical drugs for breast cancer management, such as 5-Fluorouracil, exhibited dramatically increased sensitivity to DNASE2 and ATOH8 expression." (PMID 40282270, 2025). "Here, we report that ATOH8-V1, a novel isoform of ATOH8, is highly expressed in breast cancer and is a negative prognostic indicator of survival for patients." (PMID 33049034, 2021). "Previous studies demonstrated that the expression of ATOH8 was activated by a shear-stress-responsive in endothelial differentiation and phenotypic modulation, or IL6-STAT3 signaling in breast cancer, or inhibited by promoter methylation in part of HCC cell lines." (PMID 27049918, 2016). "ATOH8’s inhibitory effect on cell migration and invasion contrasts with DNASE2’s promotion of these cellular processes, suggesting that their distinct roles could be leveraged in developing targeted therapies to modulate breast cancer progression." (PMID 40282270, 2025). "Interestingly, a most recent study has identified a novel isoform of Atoh8 called Atoh8-V1 in breast cancer, it was shown to be a negative prognostic marker with a high expression." (PMID 35053134, 2022). "In addition, this study found the following tissue specific TFs that were not reported in breast cancer: ATOH8, DMRT2, TBX15 and ZNF367." (PMID 28036274, 2017). "Given the challenges associated with experimental studies on TTC23, we have decided to further investigate the biological functions of two genes, ATOH8 and DNASE2, which have not been extensively studied in breast cancer." (PMID 40282270, 2025).
hepatocellular carcinoma (6 papers, 2017 to 2025). A malignant tumor that arises from hepatocytes. "Cancer types such as nasopharyngeal carcinoma, hepatocellular carcinoma, and non-small cell lung cancer show significant downregulation of Atoh8 expression in tumor tissue." (PMID 41440013, 2025). "In hepatitis B virus-associated hepatocellular carcinomas (HCC), reduced levels of Atoh8 were observed to be correlated with loss of tumor differentiation." (PMID 35053134, 2022). "In nasopharyngeal carcinomas (NPC), similar to the findings in hepatic carcinomas, the inhibition of Atoh8 was shown to enhance the malignant phenotype, whereas its transgenic expression was shown to reverse the phenotype." (PMID 35053134, 2022). "Down-regulated ATOH8 has been proven to contribute to the malignant phenotype of nasopharyngeal carcinoma and increases the stem cell features of hepatocellular carcinoma cells." (PMID 28036274, 2017). "Additionally, the authors have also evaluated the effect of overexpression of Atoh8 in the hepatic carcinoma cell lines, which resulted in the reduction of the proliferation along with reduced invasive and migratory abilities of those cells." (PMID 35053134, 2022). "In hepatocellular carcinoma (HCC), Atoh8 expression was consistently downregulated in tumor tissues compared to adjacent non-tumor tissues." (PMID 41440013, 2025). "Confirming the same, analysis of additional hepatic carcinoma cell lines such as HepG2, PLC8024 and CRL8064 also revealed a correlation between reduced Atoh8 expression and increased CD133 positive population." (PMID 35053134, 2022). "A study performed on hepatocellular carcinomas (HCC), however, emphasized Atoh8 as a potential tumour suppressor gene, the absence of which imparts stem cell properties to cancer cells." (PMID 31159500, 2019).
colorectal cancer (5 papers, 2019 to 2025). A primary or metastatic malignant neoplasm that affects the colon or rectum. "The GWAS catalog reports that SNPs in the ATOH8 are suggestively associated with optic disk size, abdominal aortic aneurysm, total blood homocysteine level, total cerebrospinal fluid paired helical filament-tau level, and metastasis in low/stable colorectal cancer." (PMID 36704746, 2022). "Another study, which used colorectal cancer cells as mimics of circulating tumor cells (m-CTCs), showed Atoh8 as a mechanosensor following their exposure to laminar shear stress." (PMID 35053134, 2022). "For instance, in endothelial cells and podocytes Atoh8 has been identified as a negative regulator of proliferation while in chondrocytes (this study), in regenerating mouse myoblasts and in colorectal cancer Atoh8 seems to activate the proliferation rate." (PMID 31449527, 2019). "However, other research indicated that ATOH8 promoted vascular survival of colorectal cancer cells through transcriptional activation of HK2-mediated glycolysis." (PMID 40282270, 2025). "In summary, LSS can trigger the ATOH8 upregulation in m-CTCs, which may affect hematogenous metastasis and prognosis of colorectal cancer." (PMID 32000836, 2020). "In addition, Atoh8 has been described as an activator of proliferation during muscle regeneration and in colorectal cancer." (PMID 31449527, 2019). "In colorectal cancer (CRC), higher expression of Atoh8 was found to correlate with the poor prognosis of CRC patients." (PMID 35053134, 2022). "ATOH8 then transcriptionally activated HK2-mediated glycolysis, thus promoting the intravascular survival of colorectal cancer cells in the circulation." (PMID 32000836, 2020). "Here, starting from the LSS-response molecule, ATOH8, we have unravelled a mechanism by which LSS promotes colorectal cancer cells survival in the circulation and may ultimately lead to hematogenous metastasis." (PMID 32000836, 2020).
glioblastoma (4 papers, 2016 to 2022). The most malignant astrocytic tumor (WHO grade IV). "Subsequently, Atoh8 was found to be differentially regulated in renal carcinoma cells and glioblastoma stem cells treated with retinoic acid." (PMID 31159500, 2019). "Contradictory literature exists with regard to Atoh8, as it was first described as a possible oncogene based on its copy number in a study performed on glioblastoma stem cells." (PMID 31159500, 2019). "In cancer studies, ATOH8 was first proposed as an oncogene in glioblastoma multiform only because of the copy number amplifications." (PMID 27049918, 2016). "Likewise, another study which was performed to ascertain the copy number variations in glioblastomas has also revealed aberrant expression of Atoh8 further suggesting it as a potential candidate involved in carcinogenesis." (PMID 35053134, 2022). "ATOH8, or atonal homolog 8, has been shown to be both tumor suppressive and oncogenic in other cancers, but has not been investigated in glioblastoma." (PMID 35409289, 2022).
glioma (4 papers, 2008 to 2022). A benign or malignant brain and spinal cord tumor that arises from glial cells (astrocytes, oligodendrocytes, ependymal cells). "This confirmed that gliomas with 1p19q codeletion overexpressed neuronal/normal brain genes (AKR1C3, C20orf42, CTTNBP2, L1CAM, GALNT13) as well as genes implicated in gliogenesis and neurogenesis (OLIG2, BMP2, NOG, DCX, ATOH8)." (PMID 18492260, 2008). "Higher expression of Atoh8 was found to be correlated with the pro-neural group of gliomas particularly oligodendroglioma with ‘1p19q codeletion’ and lower expression of Atoh8 was found to be correlated with a proliferative and mesenchymal group of gliomas with ‘EGFR amplification’." (PMID 35053134, 2022). "In 2008, a study performed to understand the two mutually exclusive groups of gliomas carrying ‘1p19q codeletion’ and ‘EGFR amplification’, identified Atoh8 as one of the multiple differentially regulated genes." (PMID 35053134, 2022).
nasopharyngeal carcinoma (4 papers, 2016 to 2025). A carcinoma arising from the nasopharyngeal epithelium. "Here we found that LMP1 inhibited transcription factor ATOH8 expression to endow the malignant phenotype of nasopharyngeal carcinoma." (PMID 27049918, 2016). "We found ATOH8 inhibition correlated with mesenchymal status and contributes to the malignant phenotype of nasopharyngeal carcinoma." (PMID 27049918, 2016). "Similarly, Atoh8 has been observed to be downregulated in nasopharyngeal carcinoma (NPC) tissues and derived cell lines." (PMID 41440013, 2025).
prostate carcinoma (4 papers, 2014 to 2023). A carcinoma that arises from epithelial cells of the prostate gland. "By inspection, we also identified at least 10 additional transcription factors within 500 kb of 9 other GWAS loci, that are also reasonable candidates for contributing to prostate cancer risk: SOX13, ZFP36L2, ATOH8, DLX1 & DLX2 (same locus), GATA2, SKIL, SP8, ASCL2, and DPF1." (PMID 24497837, 2014).
diabetes (3 papers, 2012 to 2024). "Conversely, β-cell-specific ATF4 knockout (βAtf4-KO) mice exhibit exacerbated diabetes, with increased dedifferentiation markers and a reduced expression of the Atonal homolog 8 transcription factor (Atoh8)." (PMID 39057094, 2024). "In addition, compounds that can target the downstream factors of ATF4, such as ATOH8, can act as potential therapeutic agents for diabetes." (PMID 34547510, 2021).
lung carcinoma (3 papers, 2016 to 2025). "Moreover, lung cancer metastasis is inhibited by CYP3A5 through regulation of the ATOH8/Smad1 axis." (PMID 39754188, 2025). "However, this is the first study implicating ATOH8 with lung cancer development." (PMID 31503425, 2019).
pulmonary arterial hypertension (3 papers, 2021 to 2022). Pulmonary arterial hypertension (PAH) is a group of diseases characterized by mean pulmonary artery pressure >20 mmHg and elevated pulmonary arterial resistance leading to right heart failure. "Moreover, the same study also identified that Atoh8 knockout mice suffer from a condition similar to pulmonary arterial hypertension which is reported to have high morbidity and mortality in humans particularly during pregnancy." (PMID 35053134, 2022). "Moreover, BMP signaling could also attenuate hypoxic responses in ECs through the ALK1/SMAD/ATOH8 axis, ultimately impeding the development of pulmonary arterial hypertension (PAH)." (PMID 34235147, 2021). "The phenotype observed in Atoh8 knockout mice which was similar to pulmonary arterial hypertension together with the reduced levels of the eNOS following knock-down or absence of Atoh8 correlates with the phenotype of defective placental development observed in Atoh8 knockout mice." (PMID 35053134, 2022). "The ATOH8 gene participates in the ALK-1/SMAD/ATOH8 axis, which attenuated the hypoxic response in endothelial cells in the pulmonary circulation and might help prevent the development of pulmonary arterial hypertension." (PMID 33936161, 2021).
anaemia (2 papers, 2014 to 2022). "Liver Atoh8 levels were reduced in mice under conditions associated with increased erythropoietic activity such as hypoxia, haemolytic anaemia, hypotransferrinaemia and erythropoietin treatment and increased by inhibitors of erythropoiesis." (PMID 24236640, 2014).
bladder cancer (2 papers, 2016 to 2023). "In the current study, ATOH8 was downregulated in the high-risk group, suggesting that it was a protective factor for bladder cancer which might due to its negative correlation with immune cell infiltration." (PMID 37968767, 2023).